RN7SKP139 (RN7SK pseudogene 139)
Gene: Miscellaneous RNA gene on chromosome 15 (47,272,597 to 47,272,889, forward strand). Ensembl gene ENSG00000222343.
Homologues: Orthologues: chimpanzee 7SK (96% identical), guinea pig 7SK (71% identical), guinea pig 7SK (63% identical). Paralogues in human: RN7SKP180 (77% identical), RN7SKP163 (76% identical), RN7SKP28 (76% identical), RN7SKP37 (76% identical), RN7SKP9 (75% identical), RN7SKP176 (75% identical), 7SK (75% identical), RN7SKP243 (75% identical), RN7SKP124 (74% identical), RN7SKP203 (74% identical), RN7SKP255 (74% identical), RN7SKP74 (74% identical), and 284 more.